NKRF (NFKB repressing factor)
Description:
Enhances the ATPase activity of DHX15 by acting like a brace that tethers mobile sections of DHX15 together, stabilizing a functional conformation with high RNA affinity of DHX15. Involved in the constitutive silencing of the interferon beta promoter, independently of the virus-induced signals, and in the inhibition of the basal and cytokine-induced iNOS promoter activity. Also involved in the regulation of IL-8 transcription. May also act as a DNA-binding transcription regulator: interacts with a specific negative regulatory element (NRE) 5'-AATTCCTCTGA-3' to mediate transcriptional repression of certain NK-kappa-B responsive genes.
Synonyms: NRF; ITBA4; XTBD3
Tractability: Small molecule: a structure with a bound ligand is known. PROTAC: UniProt records ubiquitination sites on it; ubiquitination databases record sites on it; its protein half-life has been measured.
Target class: Transcription factor
Gene: Protein-coding gene on chromosome X (119,588,337 to 119,606,443, reverse strand). Ensembl gene ENSG00000186416.
Subcellular location: Nucleus, nucleolus
Subcellular location (Human Protein Atlas): Nucleoli; Nucleoplasm
Gene Ontology:
Molecular function: ATPase activator activity; DNA-binding transcription activator activity, RNA polymerase II-specific; protein binding; RNA binding; RNA polymerase II cis-regulatory region sequence-specific DNA binding; nucleic acid binding
Biological process: negative regulation of DNA-templated transcription; positive regulation of transcription by RNA polymerase II
Cellular component: nucleolus; nucleus; nucleoplasm
Homologues: Orthologues: chimpanzee NKRF (100% identical), dog NKRF (98% identical), pig NKRF (98% identical), rabbit NKRF (97% identical), guinea pig NKRF (96% identical), mouse Nkrf (95% identical), rat Nkrf (94% identical), macaque STEEP1 (94% identical), tropical clawed frog nkrf (53% identical), zebrafish nkrf (47% identical), Drosophila melanogaster CG31301 (11% identical), Caenorhabditis elegans paxt-1 (8% identical). Paralogues in human: CDKN2AIP (12% identical), XTBD1 (1% identical).
Diseases named in the same sentence as NKRF in open-access papers:
NKRF is named in the same sentence as 37 diseases in open-access papers, as found by Europe PMC text mining. Sharing a sentence is not in itself a finding about the gene and the disease. The quoted sentences say what the papers report.
lung carcinoma (3 papers, 2020 to 2025). "Additionally, miR-192 may contribute to lung cancer progression by promoting cisplatin resistance and inhibiting apoptosis through the downregulation of NKRF or BIM." (PMID 40087755, 2025). "Similarly, miR-192 downregulates the target gene NKRF to directly activate NF-κB, which contributes to tumorigenesis by inhibiting cell apoptosis, enhancing cell cycle progression, and promoting chemo-resistance in lung cancer." (PMID 40087755, 2025).
breast carcinoma (2 papers, 2020). "Finally, we focused on NKRF as a key TROJAN-interacting protein in ER+ breast cancer." (PMID 32393270, 2020). "In addition, we found that NKRF was a key interacting protein with TROJAN in ER+ breast cancer." (PMID 32393270, 2020).
pulmonary TB (2 papers, 2013 to 2014). "In alveolar macrophages and peripheral blood mononuclear cells of pulmonary TB patients, knockdown of NKRF significantly increased IP-10 and IL-8 release." (PMID 25135111, 2014). "Our previous study showed NF-κB repressing factor (NKRF) is upregulated in the circulating monocytes and alveolar macrophages of patients with active pulmonary TB, and inhibits synthesis and release of IP-10 and IL-8." (PMID 25135111, 2014). "The results of this in vitro study are consistent with the findings of our previous study that NKRF up-regulated expression in alveolar macrophages and peripheral blood monocytes of active pulmonary TB patients represses IP-10 and IL-8 synthesis and release." (PMID 25135111, 2014). "However, NKRF was found up-regulated to repress IP-10 and IL-8 release only in pulmonary TB patients with high bacterial load." (PMID 25135111, 2014).
Alzheimer disease (1 paper, 2024). A progressive, neurodegenerative disease characterized by loss of function and death of nerve cells in several areas of the brain leading to loss of cognitive function such as memory and language. "The results of the analysis demonstrated significant inhibition in the progression of Alzheimer's disease (AD) in NKRF knock‐in (NKRF) and ZBTB17 knockout (ZBTB17−/−) mice compared to the model mice (3×Tg and 3×Tg/ApoE−/− + HFD)." (PMID 38738952, 2024). "Our CRISPR‐based study highlights the therapeutic potential of targeting NKRF and ZBTB17 expressions to manage Alzheimer's disease (AD) and atherosclerosis (AS)." (PMID 38738952, 2024). "Our study reveals common molecular pathways in Alzheimer's disease (AD) and atherosclerosis (AS), notably in genes like BEX2, NKRF, SOD1, UBL5, ZBTB17, and ZNHIT3." (PMID 38738952, 2024). "Therefore, we speculate that NKRF and ZBTB17 may regulate the progression of Alzheimer's disease (AD) and atherosclerosis (AS) by modulating NF‐κB and its related signaling pathways in microglia and macrophages." (PMID 38738952, 2024).
hypertensive (1 paper, 2023). "Hence, future studies are needed to uncover the regulatory effects of NKRF on hypertensive cardiac remodeling." (PMID 37667861, 2023).
hypospadias (1 paper, 2020). Hypospadias is the displacement of the urethral meatus on the ventrum of the penis. "And the deletion encompassing SLC25A43, LOC100303728, SLC25A5, CXorf56, UBE2A, NKRF, and SEPT6, is associated with hypospadias." (PMID 32515122, 2020).
irritable bowel syndrome (1 paper, 2024). Irritable bowel syndrome (IBS) is a chronic functional condition of the lower gastrointestinal (GI) tract characterized by abdominal pain or discomfort and disordered bowel habit (diarrhea, constipation, or fluctuation between the two). "Another interesting miRNA is certainly miR-29 since its expression downregulates CLDN1 and NKRF, leading to increased intestinal permeability, as observed in studies on knockout mice and in tissue samples from patients with irritable bowel syndrome (IBS)." (PMID 39683426, 2024).
liver cancer (1 paper, 2025). An epithelial or non-epithelial malignant neoplasm that arises from the liver. "However, the expression of NF-κB repressing factor (NKRF), the reported target gene of miR-301a-3p, was upregulated at both the mRNA and protein levels in liver cancer tissues." (PMID 40083930, 2025).
lung adenocarcinoma (1 paper, 2026). A carcinoma that arises from the lung and is characterized by the presence of malignant glandular epithelial cells. "We identify NF-κB repressing factor (NKRF) as a critical suppressor of Osimertinib resistance, whose expression is markedly reduced in resistant lung adenocarcinoma cells." (PMID 42026030, 2026).
pancreatic cancer (1 paper, 2014). "For instance, miR-301 can be induced by NF-κB signaling in pancreatic cancer cells to target NF-κB repressing factor (NKRF), which in turn inhibits NF-κB signaling in pancreatic cancer." (PMID 25275294, 2014).
renal carcinoma (1 paper, 2024). A carcinoma arising from the epithelium of the renal parenchyma or the renal pelvis. "A1CF inhibits p65(p-S536) phosphorylation and IFNβ expression and its accumulation in the nucleus depends on the interaction with NKRF, and the A1CF-NKRF-p65/IFNβ signaling axis is important to renal carcinoma growth." (PMID 38612387, 2024). "The results of anchorage-independent growth and Western blot analysis in renal cancer cells indicated that the A1CF and NKRF interaction modulates anchorage-independent growth through p65 and IFN-β in renal carcinoma cells." (PMID 38612387, 2024). "Whole-cell lysates were prepared from stable renal cancer cells with disrupted A1CF expression, and we detected the upstream and downstream regulators of NKRF and NF-κB." (PMID 38612387, 2024).
tumor (8 papers, 2017 to 2025). "Our results confirmed the roles of β‐catenin, SMAD2, and SMAD3 in promoting EMT, and identified the roles of tumor suppressor MYBBP1A, NKRF, and MYPOP in repressing the EMT process." (PMID 37566765, 2023). "After excluding general RNA-binding proteins, four potential tumor progression-related proteins (TAF15, HNRPK, NKRF and PTBP3) were identified." (PMID 32393270, 2020).
cancer (4 papers, 2012 to 2020). A tumor composed of atypical neoplastic, often pleomorphic cells that invade other tissues. "miRNA-1290 could repress NKRF to enhance NF-κB activities, which may be involved in the development and progression of cancer." (PMID 22536353, 2012).
infection (4 papers, 2013 to 2020). The state of being infected such as from the introduction of a foreign agent such as serum, vaccine, antigenic substance or organism. "Since NF-κB has a central role in regulating the cellular response to infection and activates transcription of cytokines and survival functions, the down-regulation of NKRF in infected macrophages is a logical finding." (PMID 32835600, 2020). "We aimed to analyse red sea bream NKRF (PmNKRF) gene expression after infection with pathogens [Streptococcus iniae or red sea bream iridovirus (RSIV)] and in healthy individuals." (PMID 31193988, 2019). "The up-regulated NKRF serves as an endogenous repressor for IP-10 and IL-8 synthesis to hinder host from robust response to MTb infection." (PMID 25135111, 2014).
NKRF also shares sentences with these, for which no sentence is quoted: Nephropathy (4 papers); Obesity (3); chronic obstructive pulmonary disease (2); colitis (2); amyotrophic lateral sclerosis (1); Arthritis (1); atherosclerosis (1); bacterial infection (1); cervical cancer (1); colon tumors (1); colorectal cancer (1); COVID-19 (1); cystitis (1); Disc Degeneration (1); gastric cancer (1); lactic acidosis (1); Left ventricular dilatation (1); Lung Injury (1); neuroblastoma (1); neurodegenerative disease (1); osteosarcoma (1); triple-negative breast carcinoma (1); tuberculosis (1).